PTH (parathyroid hormone)
Diseases named in the same sentence as PTH in open-access papers (continued):
Sharing a sentence is not in itself a finding about the gene and the disease.
parathyroid disease (24 papers, 2008 to 2025). "They account for about 10% of all PHPT cases and are often associated with multi-glandular parathyroid disease and early onset of parathyroid hormone (PTH) excess." (PMID 40364143, 2025). "Overproduction of PTH results in elevated calcium levels and decreased phosphate, which underlies the symptoms seen in parathyroid disease." (PMID 39427404, 2024). "Parathyroid diseases are heterogeneous conditions that are generally caused by alterations in PTH secretion, resulting in dysregulation of calcium homeostasis." (PMID 36306782, 2022). "Possible association between PTH alterations and the diverse manifestation of MetS have been proposed and it could be supposed that MetS may negatively influence parathyroid diseases." (PMID 36773188, 2023). "The patient had raised serum parathyroid hormone and serum calcium levels, suggesting parathyroid disease." (PMID 39170840, 2024). "Parathyroid diseases are related to parathyroid hormone (PTH) dysregulation by parathyroid cells or alteration of PTH function." (PMID 36773188, 2023). "An additional 45% had levels of parathyroid hormone that were in the normal range, most likely inappropriately normal for the concomitant level of calcium, consistent with a possible parathyroid disease as well." (PMID 36843806, 2023). "Parathyroid diseases are characterized by dysregulation of calcium homeostasis and alterations in parathyroid hormone (PTH) excretion." (PMID 36306782, 2022). "This suspicious presentation of benign disease, including a marked elevation in PTH, highlights the challenges facing the endocrine surgeon in dealing with parathyroid disease." (PMID 21209735, 2010). "It should be emphasised that elevated PTH values, and slightly decreased calcium levels, can be associated with VitD deficiency in the absence of parathyroid disease." (PMID 36835987, 2023). "Interesting findings revealed from a comprehensive study of patients with the uniglandular parathyroid disease are that a high PTH level, pathologic parathyroid gland volume, weight, and oxyphil cell content were all significantly associated with MIBI positivity." (PMID 37892003, 2023). "However, possibly because of lack of PTH stimulation caused by parathyroid gland disorders, there was a reduction in renal excretion of phosphorus and a progressive increase in blood levels of this ion, in contrast to the reduction in calcium." (PMID 21181066, 2010). "In fact, sporadic cases of markedly elevated PTH have been reported in human patients with AKI without evidence of parathyroid gland disorders, as well as cases of transient PTH increase during AKI that normalized completely after recovery within 48 h." (PMID 40005891, 2025). "This meant that a thorough workup for parathyroid disease, such as preoperative measurement of PTH and vitamin D levels, was not performed." (PMID 22091440, 2011). "Two patients did not have preoperative calcium checks, and none of our patients had preoperative parathyroid hormone (PTH) or vitamin D levels, as parathyroid disease was not suspected before surgery." (PMID 22091440, 2011).
periodontitis (24 papers, 2015 to 2025). An acute or chronic inflammatory process that affects the tissues that surround and support the teeth. "In turn, the biochemical findings showed an increase in PTH and a decrease in 25OH vitamin D to be associated with a loss of bone density, and such patients moreover presented advanced stage periodontitis." (PMID 39582410, 2025). "Topical and intermittent application of PTH has also been reported to aid in alveolar bone loss recovery in rat periodontitis." (PMID 33172437, 2020). "In this study, we investigated the effect of intermittent PTH administration on alveolar bone loss in type 1 diabetic rats with periodontitis." (PMID 29544500, 2018). "In ovariectomized rats with periodontitis, intermittent PTH administration was shown to reduce alveolar bone loss." (PMID 29544500, 2018). "It was reported that PTH protected against periodontitis-associated bone loss through the regulation of osteoblast activity." (PMID 28427342, 2017). "A recent report demonstrated that intermittent PTH administration was able to reduce the number of inflammatory cells at the marginal gingival area and protect against periodontitis-associated bone loss in a rodent model." (PMID 27480134, 2016). "Whereas, subjects with high level of vitamin D were also susceptible to periodontitis, for it did nothing to improve bone density but increase the risk of fracture with the suppression effect on PTH, which could active osteoclasts and reduce bone formation." (PMID 37131215, 2023). "In summary, these results indicate that intermittent PTH administration increases osteoid formation and mineralization, and diminishes alveolar bone loss and sclerostin expression in osteocytes of type 1 diabetic rats with periodontitis." (PMID 29544500, 2018). "Future studies should aim to validate these findings longitudinally and assess whether targeted interventions on PTH or VitD pathways, especially in genetically predisposed individuals, can mitigate skeletal complications in inflammatory conditions such as periodontitis." (PMID 41301518, 2025). "Our biochemical results showed that the increase in PTH and the decrease in 25OH VIT-D were associated with loss of bone density and these patients presented advanced periodontitis." (PMID 39582410, 2025). "Remarkably, pre-clinical studies and clinical trials have already revealed promising outcomes when administrating PTH or PTHrP in various dental-related diseases, such as periodontitis, osteonecrosis of the jaw, and jawbone defects." (PMID 34760881, 2021). "A variety of studies using both animal models and clinical trials have suggested a promising outcome for PTH treatment in periodontitis." (PMID 34760881, 2021). "PTH-treated periodontitis rodents had reduced alveolar bone resorption and milder infiltration of inflammatory cells at the marginal gingiva." (PMID 34760881, 2021). "Taken together, decreased sclerostin expression in osteocytes after intermittent PTH administration appears to be involved in the increase in bone formation observed in type 1 diabetic rats with periodontitis." (PMID 29544500, 2018). "In both rats with periodontitis and ovariectomized rats with periodontitis, anabolic effects on alveolar bone were induced by PTH administration three times per week for 1 month." (PMID 29544500, 2018). "As in study of rats with periodontitis treated intermittently with PTH, we also found greater osteoid area in alveolar bone of the DP + PTH group compared to the DP group." (PMID 29544500, 2018). "Based on the data generated by these two groups, we administered PTH three times per week for 1 month in type 1 diabetic rats with periodontitis." (PMID 29544500, 2018). "Another research reported that higher serum PTH might cause CKD animals to exhibit lower mandible bone volume in the region of the first mandible molar and a phenotype consistent with periodontitis." (PMID 40421989, 2025).
periodontitis (continued). "However, future studies should focus on the interplay among the serum levels of vitamin D, calcium, parathyroid hormone, metabolic dysfunction, and periodontitis." (PMID 36618706, 2022). "Furthermore, there is growing knowledge of the therapeutic application of PTH and PTHrP analogs in dental implant surgery, orthodontics, periodontitis, and orofacial regeneration medicine." (PMID 34760881, 2021). "Therefore, we investigated the anabolic effects of intermittent PTH administration in rats with streptozotocin (STZ)-induced type 1 diabetes accompanied by periodontitis." (PMID 29544500, 2018). "In addition, mineral deposition in alveolar bone was greater in the DP + PTH group than in the DP group, suggesting an anabolic effect of PTH on alveolar bone in type 1 diabetic rats with periodontitis." (PMID 29544500, 2018). "PTH-induced bone formation may be related to the regulation of osteocytic sclerostin expression in type 1 diabetic rats with periodontitis." (PMID 29544500, 2018). "In this study, we aimed to determine whether PTH affected the osteogenic capacity of STRO-1(+) PDLSCs in order to analyze the potential applications of these cells in the treatment of periodontitis." (PMID 27069479, 2016). "In this study, we hypothesized that PTH would affect the osteogenic capacity of PDLSCs and show the potential for application as a cell source in periodontitis treatment." (PMID 27069479, 2016). "However, PTH treatment had a positive effect on periodontitis in a diabetic rodent model." (PMID 34760881, 2021). "Moreover, local injection of PTH, or PTH in combination with neutral self-assembling peptide hydrogel, could improve clinical outcomes of chronic periodontitis." (PMID 34760881, 2021). "Therefore, in this study, we aimed to compare the functions of STRO-1(+) and STRO-1(−) hPDLSCs and to investigate the effects of PTH on the osteogenic capacity of STRO-1(+) hPDLSCs in order to evaluate their potential applications in the treatment of periodontitis." (PMID 27069479, 2016). "A study of PTH-treated ovariectomized rats with periodontitis (three times per week) showed recovery of alveolar bone loss to levels of normal rats; these results are inconsistent to our findings, where alveolar bone loss in the DP + PTH group did not recover to levels of the C group." (PMID 29544500, 2018). "Intermittent PTH treatment improved the capacity of STRO-1(+) hPDLSCs to repair damaged tissue and ameliorate the symptoms of periodontitis." (PMID 27069479, 2016). "Intermittent PTH treatment improved the capacity for STRO-1(+) hPDLSCs to repair damaged tissue and ameliorate the symptoms of periodontitis." (PMID 27069479, 2016). "Indeed, VEH/PTH rice rats had fewer neutrophils than VEH/VEH rice rats with periodontitis, and ZOL/PTH rice rats had fewer neutrophils than ZOL/VEH rats with MRONJ." (PMID 37404809, 2023). "Furthermore, since SDF-1α and PTH can both promote proliferation and osteogenic differentiation of PDLSCs, PTH/SDF-1α co-therapy becomes a promising strategy for periodontitis." (PMID 34760881, 2021). "Our results showed that PTH could stimulate osteogenesis in STRO-1(+) hPDLSCs, suggesting that this population of cells could be used in tissue regeneration to repair periodontitis-dependent bone damage." (PMID 27069479, 2016). "However, the effects of PTH on alveolar bone formation and osteocytic sclerostin expression of rats with both periodontitis and type 1 diabetes have been not determined." (PMID 29544500, 2018). "Other studied parameters, including PTH, TSH, T3, T4, cortisol, human-grown hormone, platelets count, total proteins, CRP, and fecal calprotectin, were all nonsignificantly different and without correlation depending on the presence of periodontitis." (PMID 40559437, 2025).
periodontitis (continued). "This study aims to compare the level of FGF23 in predialysis CKD patients with periodontitis, predialysis CKD patients without periodontitis, periodontitis patients without CKD, and healthy population and determine their correlation with phosphate, calcium, and intact parathyroid hormone (iPTH)." (PMID 39176315, 2024).
cardiac arrhythmia (23 papers, 2013 to 2026). Any disturbances of the normal rhythmic beating of the heart or MYOCARDIAL CONTRACTION. "In particular, an increased risk for cardiac arrhythmia as a result of their anti-dopaminergic activity and inhibition of hERG channels could impede repositioning of some of these PTH for the treatment of PCa due to potential concerns by regulatory agencies." (PMID 32905878, 2020). "The potent dopamine antagonist activity of some PTH antipsychotics has been blamed for some of the lethargic and extrapyramidal effects, as well as for the cardiac arrhythmia." (PMID 32905878, 2020). "The syndrome of HHHP is commonly found in PPIH due to hypomagnesaemia interfering with PTH and Ca homeostasis, and should be considered in any patient presenting with cardiac arrhythmia, neuromuscular irritability or weakness." (PMID 25138239, 2015). "Clinical studies in chronic dialysis patients have suggested a U-shaped relationship between PTH and sudden death, probably due to arrhythmia." (PMID 23762460, 2013). "Abnormal electrolyte concentrations may be associated with kidney function or hormonal disorders (such as aldosterone or parathyroid hormone), and K+ imbalances can lead to cardiac arrhythmias." (PMID 37896177, 2023). "Additionally, the alternation of left ventricle mass thickening and arrhythmia triggered by PTH hyperfunction results in metabolic variables and cardiovascular risk as noted in epidemiological studies." (PMID 37424030, 2023). "It is important to consider calcium and parathyroid hormone levels in patients with recurrent VT/VF without any obvious cause of arrhythmia." (PMID 31624606, 2019). "The higher the COPD group (Global Initiative for Chronic Obstructive Lung Disease (GOLD) D), the lower vitamin D ​​and the higher PTH levels were." (PMID 39114236, 2024). "As expected, we found low levels of PTH in the HG, and a slightly higher mean in the CG, without difference in presence of arrythmia." (PMID 38578437, 2024).
hip fracture (23 papers, 2010 to 2025). Traumatic or pathological injury to the hip in which the continuity of either the femoral head, femoral neck, intertrochanteric or subtrochanteric regions is broken. "Higher intact PTH levels were also associated with an increased risk of hip fracture: the magnitude of the excess risk was greater than that for any fracture." (PMID 39430172, 2024). "In stratified analysis, the association between intact PTH levels and the risk of any fracture or hip fracture was largely consistent across most strata." (PMID 39430172, 2024). "Although the association between PTH levels and the relative risk of any fracture or hip fracture was largely consistent across subgroups, there was substantial variation in the absolute risk difference." (PMID 39430172, 2024). "Consistent with our results, Amphansap and coworkers reported that osteoporotic hip fracture patients with vitamin D inadequacy (insufficiency and deficiency) had higher PTH levels than those with vitamin D sufficiency." (PMID 36834562, 2023). "The importance of the assessment of serum βCTX as a possible risk factor for hip fracture is supported by the fact that βCTX, similar to PTH, is significantly related to the CCI and the presence of previous fragility fractures." (PMID 35742610, 2022). "Results from our network meta-analysis show that PTH ranks first in reducing risk of hip fracture and second in increasing BMD at lumbar spine." (PMID 34300210, 2021). "Low hemoglobin, total leukocyte count and albumin, as well as high creatinine and parathyroid hormone (PTH) levels are associated with a higher probability of death after one year in hip fracture patients." (PMID 26833068, 2016). "Besides, a recent study using Dialysis Outcomes and Practice Patterns Study (DOPPS) showed that low PTH had a significant association with reduced hip fracture risk." (PMID 39188768, 2024). "Our results show that serum PTH level may be an effective indicator of hip fracture delayed healing risk in the elderly." (PMID 31718681, 2019). "As expected, hip fracture patients presented significantly lower 25OHD serum levels and significantly higher levels of PTH and β-CTX with respect to controls." (PMID 35742610, 2022). "Considering both the effectiveness of increasing BMD and preventing hip fracture, mAb, BP, and PTH are more favorable among all interventions." (PMID 34300210, 2021). "Considering both the effectiveness of increasing BMD at total hip and preventing hip fracture, mAb, BP, and PTH are more favorable among all interventions." (PMID 34300210, 2021). "Considering simultaneously the effectiveness of increasing BMD at total hip and preventing hip fracture, mAb, BP, and PTH are more favorable among all interventions." (PMID 34300210, 2021). "Results from clustered ranking plot show that considering both the effectiveness of increasing BMD at total hip and preventing hip fracture, mAb, BP, and PTH are more favorable among all interventions." (PMID 34300210, 2021). "This study examined serum PTH levels in elderly male patients with hip fracture at different times and explored its relationship with fracture healing." (PMID 31718681, 2019). "The aim of the present study was to investigate the relationships between serum 1,25(OH)2D, 25(OH)D, parathyroid hormone (PTH), bone turnover markers on femoral bone structure in a cross-sectional study of elderly hip fracture patients." (PMID 31731695, 2019). "Original published studies of vitamin D, PTH and hip fracture were identified through PubMed and Web of Science databases, searches of reference lists and forward citations of key papers." (PMID 20540727, 2010). "We undertook separate meta-analyses of RCTs examining vitamin D supplementation and hip fracture, and observational studies of serum vitamin D status (25-hydroxyvitamin D (25(OH)D) level), PTH and hip fracture." (PMID 20540727, 2010).
hip fracture (continued). "Results from case-control studies were combined using the ratio of 25(OH)D and PTH measurements of hip fracture cases compared with controls." (PMID 20540727, 2010). "Two of the studies showed significantly higher PTH levels in hip fracture patients compared to controls while two studies showed relationships in the opposite direction with significantly lower PTH levels in the hip fracture patients compared to controls." (PMID 20540727, 2010). "The median intact PTH level was 141 pg/ml (interquartile range, 78–226 pg/ml), the mean ± SD serum calcium level was 9.1 ± 0.7 mg/dl, the mean ± SD serum phosphorus level was 5.2 ± 1.4 mg/dl, and 4.5% of participants had a history of hip fracture." (PMID 39430172, 2024). "The relationship between PTH levels and fracture risk was particularly evident for hip fracture, to which cortical rather than trabecular bone porosity contributes more." (PMID 39430172, 2024). "Hip fracture risk was associated with elevated PTH and not directly with vitamin D levels or the residency status." (PMID 26910625, 2016). "Ten eligible case-control studies of PTH and hip fracture were identified." (PMID 20540727, 2010). "Hip fracture risk was associated with the elevated PTH and not directly to the vitamin D levels." (PMID 26910625, 2016). "Parathyroid hormone reduced time to union in several clinical trials performed in mainly hip fracture patients, but this did not result in decreased delayed or non-union rates." (PMID 34458509, 2021).